RAG1 (recombination activating 1)
Diseases named in the same sentence as RAG1 in open-access papers (continued):
Sharing a sentence is not in itself a finding about the gene and the disease.
colitis (continued). "A more complex scenario emerged however from studies in chronic CD45RB (high) CD4+ T cell transfer and anti-CD40 antibody-induced acute innate colitis models in Rag1-deficient mice showing that IL-23R signaling in ILCs3 is protective in the former and pathogenic in the latter." (PMID 25061260, 2014). "Finally, to test if the ablation of PP4 enhanced the overall colitogenic ability of peripheral T cells, we adoptively transferred WT or PP4-deficient CD4+CD45RBhi cells into RAG1-/- recipients to induce experimental colitis." (PMID 24904742, 2014). "Only when we adoptively transferred TR2-deficient cells into a completely lymphopenic environment (RAG-1 deficiency), strong colitis developed within 30 d (E and unpublished data), which was accompanied by a massive infiltration of CD4+ T cells to mesenteric lymph nodes." (PMID 24115907, 2013). "Differences in the immunopathology and applied experimental animal models, e.g., adoptive transfer of naïve or antigen-sensitized T cells to Rag1−/− and wt mice, respectively, might well explain the opposing outcome of Scd1 deficiency on disease initiation and severity in the colitis and EAE model." (PMID 37041314, 2023). "However, an important question remaining to be answered is whether the Asc−/− Tregs are also potent enough to prevent the onset of exacerbated colitis caused by adoptive transfer Asc−/− naïve CD4+ T cells into Rag-1−/− recipients." (PMID 31379813, 2019). "Rag1−/− recipients of CD45Rbhi T cells and QPC iKO Tregs developed more severe colitis compared to Rag1−/− recipients of CD45Rbhi T cells and QPC iWT Tregs." (PMID 41178490, 2026). "In a transfer‐induced colitis model, Rag1–/– mice receiving Nfkbid knockout T cells developed a more severe form of colitis, characterized by an increase in IFN‐γ+ T cells and a complete loss of IL‐17A‐producing cells." (PMID 40359334, 2025). "The largest group comprised animal studies (n = 29), including various mouse models (DSS-induced colitis, IL-10 knockout, Rag1 knockout, and Casp8ΔIEC mice)." (PMID 40647225, 2025). "Compared to the Rag1−/− mice receiving CD4+CD25−CD45RBhigh T cells from SHP2f/f donors, recipients of cells from CD4‐Cre;SHP2f/f mice exhibited attenuated colitis severity, as evidenced by reduced weight loss and diminished colon shortening." (PMID 40757098, 2025). "Atg7ΔCD4 mice exhibited exacerbated result of 2,4,6‐trinitrobenzenesulphonic acid‐induced experimental colitis, as did Rag1−/− mice adoptively transferred with CD45RBhigh CD4+ T cells from Atg7ΔCD4 donors." (PMID 40887825, 2025). "Although we observed some attenuation of colitis in the distal colon of Rorc-/- x TRAG mice, the colitis was more severe compared to RAG1-/- distal colons." (PMID 38512959, 2024). "Using naive T cells extracted from hTNF‐KI donor animals, they created a mouse colitis model that was exclusively dependent on human TNF expression in the progeny of hTNF‐KI mice bred with Rag1−/− mice." (PMID 38533646, 2024). "More severe diarrhea, colitis, and colon pathology were observed in Rag1–/–RorccreCtnnb1ex3fl/wt mice than in control mice." (PMID 38561332, 2024). "We further used a T cell transfer colitis model, in which naive T cells administered to lymphopenic Rag1–/– mice resulted in severe colitis, while cotransfer of naive T cells together with Tregs attenuated the severity of colitis." (PMID 39480507, 2024). "Consistent with prior results, TRAG mice exhibited significantly higher histological scores of colitis compared to RAG1-/- mice, in the cecum, proximal and distal colon." (PMID 38512959, 2024). "To further determine the impact of Ku70 deficiency on Treg function, we isolated CD45.2+ Tregs from WT and cKO mice and then transferred them along with naive CD45.1+CD4+ T cells into Rag1–/– recipient mice to establish adoptive transfer colitis models." (PMID 39446493, 2024).
colitis (continued). "Specifically, in TNBS-induced colitis, Cd44, Numa1, S100a8, S100a9, Timp1 and Xbp1 were more highly expressed, while Cidec and Rag1 were less expressed." (PMID 38778086, 2024). "Transfer of naive T (Tnai) cells (CD4+Foxp3−CD44loCD62Lhi) into Rag1−/− recipients led to a wasting disease with colitis within 4 weeks." (PMID 37600496, 2023). "To further confirm the value of PSI-iTregs in the treatment of IBD, we applied another model of colitis, T cell transfer-induced colitis of Rag1-/- mice." (PMID 37064870, 2023). "Similar to chemically induced IBD, T-cell transfer-induced colitis in Rag1-/- mice was also significantly attenuated by PSI-iTregs while mice treated with Control-iTregs had much more damage, with more leukocyte infiltration." (PMID 37064870, 2023). "In contrast, the overexpression of BRG1 promoted T-bet-mediated suppression of GM-CSF in ILC3s, thereby ameliorating colitis in Rag1-/-Smarca4ΔILC3 mice." (PMID 36776858, 2023). "On the other hand, for T-cell-transfer-mediated colitis, Rag1 -/- and Rag2 -/- are often used interchangeably due to their phenotypic similarities." (PMID 36672648, 2023). "T cell-dependent colitis model induced by the adoptive transfer of naive T cells into Rag1 null mice and DSS-induced colitis mice model." (PMID 36466902, 2022). "In our study, we found that transfer ST4-altered microbiota from Rag1−/− mice reduces inflammation in experiment-induced colitis through an increase in “beneficial” microbes such as Akkermansia." (PMID 35435504, 2022). "The colitis in villin-TNFAIP3 × RAG1−/− (TRAG) mice is prevented by antibiotics, indicating a role for microbes in this innate colitis." (PMID 36162004, 2022). "In parallel we determined if the production of the major GPR183 ligand, 7α,25-diHC, in Rag1-/- recipient was relevant for colitis pathogenesis." (PMID 36389671, 2022). "In contrast, cotransfer of CD4+YFP+Foxp3YFP-Cre Tregs or SRC2fl/fl/Foxp3YFP-Cre Tregs with naive CD4+ T cells rescued these severe colitis phenotypes in Rag1−/− mice." (PMID 35704583, 2022). "To address this, we induced colitis by transferring of naive hTNF-KI T cells into Rag1−/− recipients and modified the microbiota in these mice by vancomycin treatment concomitantly with anti-TNF treatment." (PMID 35383266, 2022). "In this context, quercetin was demonstrated to attenuate T cell-mediated colitis in Rag1−/− mice partially by modifying macrophage function by HO-1." (PMID 35884960, 2022). "CD4+ T cells obtained from the mLNs of R23FR mice in remission (primed by TAM-induced IL-23 and Red 40 treatment) were used to transfer colitis to Rag1−/− mice treated with Red 40 in their drinking water (0.25 g/L) or diet (0.25 g/kg, TD.160647, diet 2019)." (PMID 35468944, 2022). "RAG1 KO mice develop colitis spontaneously upon infection with H. hepaticus, which is exacerbated in RAG1/ALPK1 double KO mice." (PMID 36098982, 2022). "While TNFR2 KO tTregs were unable to prevent adoptive T cell transfer-induced colitis in Rag1 KO mice, TNFR2 KO iTregs were fully suppressive." (PMID 36466853, 2022). "To address this, we used the T cell transfer model of colitis, in which Rag1−/− mice undergo T cell driven colitis when CD4+ T effector cells are adoptively transferred from donor wt mice, in the absence of Tregs." (PMID 35177818, 2022). "Itgb8-/- Tregs were capable of preventing colitis when they were co-transferred with naïve T cells to Rag1-/- mice." (PMID 34302795, 2021). "Acute colitis was induced by dextran sodium sulfate (DSS) in C57BL/6J mice, and chronic colitis was induced by naïve T cells in Rag1 KO mice." (PMID 34336843, 2021). "To address this, we tested Aβ0/0 Treg cell capacity to attenuate colitis induced by the injection of WT T naïve cells into Rag1 ko mice." (PMID 34211466, 2021).
colitis (continued). "To this purpose, we made use of a model of colitis induced by adoptive transfer of WT T cells, alone or in combination with WT or Aβ0/0 Treg cells, into Rag1 ko mice, and analyzed the capacity of Treg cells to attenuate colitis." (PMID 34211466, 2021). "For example, in an adoptive transfer model of colitis, transferring CD4+CD25- T cells from RORγt-/- mice to RAG-1-/- immunodeficient mice is unable to induce colitis, while treatment with IL-17A can restore colitis after the transfer of RORγt-/- T cells." (PMID 33754076, 2021). "Rag1-/- mice that received Themis-/- CD4+ Foxp3- T cells were resistant to developing colitis compared to the Rag1-/- mice that received Themis+/+ CD4+ Foxp3- T cells, as measured by increased body weight." (PMID 33177694, 2021). "We finally established a classic of T-cell mediated model colitis in Rag1-deficeint mice, in which a mixture of CD4+CD45RB+CD25- effector T cells plus WT or PDK1-deficient Treg cells was transferred." (PMID 34646383, 2021). "Co-transfer of CD45.2+Hif2af/f (WT) tTreg cells protected RAG-1-KO mice from CD45.1+ effector T cell-induced body weight loss, colitis, diarrhea, tissue damage and inflammatory infiltration." (PMID 33024109, 2020). "In the colitis prevention model, B6/Rag1−/− mice were adoptively transferred i.p. with 1 × 106 WT CD4+CD25− Tconv together with 5 × 105 CD4+CD25+ Treg from either WT or HDAC10−/− donors simultaneously." (PMID 31949209, 2020). "It has been reported that when wild-type (WT) naïve T cells are transferred into the lymphopenic Rag1–/– mice, the Rag1–/– mice develop colitis after 4–8 weeks." (PMID 32634481, 2020). "Cd4CreHif2af/f tTreg cells recovered from RAG-1-KO mice with colitis displayed enhanced expression of IL-17 and IFN-γ, suggesting a susceptibility to being converted into inflammatory cytokine-producing cells." (PMID 33024109, 2020). "We found that circKcnt2−/−Rag1−/− mice displayed more substantial infiltration of inflammatory cells and higher colitis scores after 8 week challenge than circKcnt2+/+Rag1−/− mice." (PMID 32796851, 2020). "We re-isolated the adoptive-transferred tTreg cells (CD45.2+) from RAG-1-KO mice after colitis induction and determined the expression of IL-17 and IFN-γ." (PMID 33024109, 2020). "By contrast, we observed increased expression of IL-17 and IFN-γ in HIF-2α-KO tTreg cells recovered from RAG-1-KO mice with ongoing colitis." (PMID 33024109, 2020). "A large proportion of RAG-1-KO mice that received Cd4CreHif2af/f tTreg cells lost body weight and developed colitis, indicating that Cd4CreHif2af/f tTreg cells have impaired in vivo suppressive activity." (PMID 33024109, 2020). "In previous studies, we had already observed that B. vulgatus impaired inflammation in T cell-transplanted Rag1-/- mice, whereas transplantation of Enterobacteriaceae-rich microbiota strongly exacerbated the course of colitis." (PMID 33542719, 2020). "The initial lack of Tregs and induction of inflammatory Th1 and Th17 cells are known to play a role in disease onset in the T cell transfer model of colitis in Rag1-/- mice." (PMID 33542719, 2020). "Additional Hif1a deletion restored the capacity of Cd4CreHif2af/f tTreg cells to suppress effector T cell-induced colitis in RAG-1-KO mice, as shown by retention of body weight and repression of colitis score." (PMID 33024109, 2020). "We found that transferring WT naïve T cells into Rag1–/– mice induced colitis in the Rag1–/– mice characterized by progressive weight loss over time." (PMID 32634481, 2020). "After elimination of ILC and chronic DSS exposure, weight loss was similar as compared with isotype and saline treated RAG‐1−/− mice with chronic DSS colitis." (PMID 32567222, 2020). "We found that HIF-1α was increased in HIF-2α-KO Treg cells re-isolated from RAG-1-KO mice with colitis." (PMID 33024109, 2020).
colitis (continued). "To delineate the role of ILC3s in TL1A/DR3-induced inflammation, we administered α-DR3 and induced DSS colitis in littermate Rag1–/–Rorcgfp/+ and Rag1–/–Rorcgfp/gfp mice." (PMID 31358760, 2019). "We therefore conclude ILC3s are indispensable for α-DR3-exacerbated DSS-induced colitis in Rag1–/– mice." (PMID 31358760, 2019). "In DSS-induced colitis in Rag1–/– mice, we found that DR3-Fc-treated mice lost less weight and had increased colon length." (PMID 31358760, 2019). "Colitis was induced in Rag1−/− mice by administration of CD4+CD25− T cells, leading to body weight loss, rectal prolapse and diarrhea." (PMID 29386580, 2018). "T cell transfer colitis was induced in RAG1−/− mice, and Foxp3tm4(YFP/cre)Ayr, αv−/− or β8−/− Treg were injected at 2.5 × 105 cells per mouse 21 days later." (PMID 29535709, 2018). "Effector T cell-induced colitis in Rag1−/− mice, which was poorly rescued by Xiap−/− tTreg cells, was prevented by co-administration of anti-IL-6R." (PMID 29386580, 2018). "To assess the function of TRIM28 in naive T cells in vivo, we used a T-cell transfer colitis model in which Rag1−/− mice were injected with CD4+CD45RBhi naive T cells isolated from WT or Trim28−/− mice." (PMID 29651155, 2018). "Similar to WT C57BL/6 mice, POM‐1 treatment increased the severity of DSS‐induced colitis in Rag1−/− mice and shortened colon length." (PMID 29758102, 2018). "To test if these changes are caused by the CD40-fusion protein or by secondary inflammatory effects due to colitis, we also analysed mice treated with ABX or on Rag1−/− background, which are free of colitis." (PMID 28276457, 2017). "To test if the development of colitis was dependent on T and B cells or commensal bacteria, we bred DC-LMP1/CD40-mice to T and B cell deficient Rag1−/− mice or treated DC-LMP1/CD40-mice with a mixture of antibiotics (ABX), respectively." (PMID 28276457, 2017). "Surprisingly, we found that after crossing to the Rag1−/− background, Nlrp3R258W mice develop notable spontaneous colitis." (PMID 29196621, 2017). "To test this we transferred naive WT, Ndfip2−/−, Ndfip1 cKO and cDKO CD4+ T cells into Rag1−/− recipients to induce colitis." (PMID 27088444, 2016). "As T- and B-cell deficient C.B-17 SCID or Rag1−/− mice also develop severe colitis, the adaptive immune system most likely does not play a major role (at least in the acute phase) in this DSS-colitis model." (PMID 25756273, 2015). "Meanwhile, Rag1−/− hosts transferred with IL-17A−/− CD4+ CD45RBhigh T cells show more severe colitis compared to Rag1−/− mice received corresponding wild type CD4+ T cells, accompanying by increased IFN-γ level in colon." (PMID 25133396, 2014). "This is consistent with published studies of the T-cell-transfer colitis model where injection of naïve T cells into syngeneic Rag1−/− mice leads to their proliferation and conversion to TEM cells." (PMID 24844383, 2014). "Such a scenario has been observed when comparing the colitis incidence between TCRα-/-, TCRβ-/- and RAG1-/- mice housed in specific pathogen-free facility." (PMID 24904742, 2014). "On the other hand, a recent study reported that p40phox−/− mice have increased inflammation and more severe colonic tissue injury in both DSS and Rag1−/− mouse models of colitis." (PMID 23613889, 2013). "DSS colitis in Rag1−/− mice induces colonic LTi-like cells to produce IL-22: the percentage of LTi-like cells producing IL-22 increases from ∼13% in healthy (control) conditions to ∼37% in inflammatory (DSS) conditions." (PMID 23750260, 2013). "Transfer into neonate Rag1−/− recipients induced little inflammation in the colon before weaning but severe colitis rapidly developed afterward." (PMID 24832045, 2012). "Transfer into neonate Rag1-/- recipient induced little inflammation in the colon before weaning but severe colitis rapidly developed within a few days after weaning." (PMID 19272184, 2009).
colitis (continued). "We investigated whether TRIP13 exerts anti-inflammatory effect through Treg expansion in a mouse colitis model induced by transferring naïve CD4+ T cells into lymphopenic Rag1−/− mice (CD45.2+)." (PMID 41535263, 2026). "The initial CD4+ T cells from spleen wild-type mice were transferred to RAG1−/− mice to establish a T cell metastatic colitis model;Rectal application of TNBS for 2 days to establish acute TNBS colitis;Mice were given DSS in drinking water for 7 days to induce colitis." (PMID 40529369, 2025). "Moreover, Rag1−/− mice were also used to establish the DSS-induced colitis model, and the results were consistent with those of the nude mice (Data not shown)." (PMID 40854873, 2025). "Ire1αΔRorc Rag1–/– mice develop exacerbated colitis upon adoptive T cell transfer." (PMID 38722686, 2024). "SCFAs, produced by microbial fermentation of dietary fibers, have been shown to induce the differentiation of regulatory T (Treg) cells in vitro and in vivo, and mitigate colitis development induced by the transfer of CD4(+) CD45RB(hi) T cells in Rag1(-/-) mice." (PMID 38903520, 2024). "In addition, Gpr109a-/-Rag1-/- mice were found to develop spontaneous colitis, and compared with Rag1-/-mice, they showed higher IL-17 production in intestinal ILC3s." (PMID 37304260, 2023). "Because of the increased expression in colonic T cells from patients with IBD, we tested the effect of GPR183 deficiency in the T cell transfer model of colitis, in which CD4+ CD45RBhigh (naïve) T cells, depleted of regulatory T cells, are adoptively transferred into Rag1-/- recipients." (PMID 36389671, 2022). "Furthermore, histopathologic scoring of the colon sections revealed that the colitis severity was similar when Gpr183-/- or control T cells were injected into Rag1-/- recipients." (PMID 36389671, 2022). "Also, we have not excluded the possibility that deletion of Gpr183 on both the donor T cells and the Rag1-/- hosts would have had an effect on colitis induction." (PMID 36389671, 2022). "Thus, we next genetically depleted TNF in myeloid cells (M-TNF−/−× Rag1−/−; TNFf/f×Mlys-Cre×Rag1−/−) and in epithelial cells (EC-TNF−/−×Rag1−/−; TNFf/f×Vil-Cre×Rag1−/−) in Rag1−/− mice and induced colitis by transfer of naive T cells from WT mice." (PMID 35383266, 2022). "Therefore, we tested if GPR18 expression by cells other than T lymphocytes, including innate immune cells in the Rag1-/- hosts, was required for colitis." (PMID 36389671, 2022). "However, after being adoptively transferred with Tregs from cLP of Foxp3eGFP reporter donor mice treated with rTsPmy or PBS, these pathological conditions were significantly reduced in Rag1 KO mice with T-cell-induced colitis." (PMID 34336843, 2021). "To test if failed suppression of aberrant T cell activity by Tregs contributed to the fatal inflammation in Dohh-ΔT and Dhps-ΔT mice, we transferred naive WT CD45.1+ CD4+ T cells into Rag1−/− recipients to initiate colitis, together with Tregs sorted from WT and Dohh-ΔT mice." (PMID 34216540, 2021). "For instance, in an adoptive transfer colitis model when Treg-depleted memory/effector CD4+CD45RBlo T cells were transferred into RAG-1-/- mice, IL-22 derived from these memory/effector T cells is pathogenic, whereas IL-22 is protective when CD4+CD45RBhi naïve T cells were transferred." (PMID 34992594, 2021). "To test these hypotheses, we utilized a T cell transfer colitis model where naïve T cells were transferred either alone or together with Treg cells into lymphopenic Rag1–/– mice." (PMID 32634481, 2020). "When WT naïve T cells were transferred with WT Treg cells into Rag1–/– mice, the WT Treg cells were able to completely suppress the naïve T cell–induced colitis with no weight loss seen after 7 weeks." (PMID 32634481, 2020).